LRG1 (leucine rich alpha-2-glycoprotein 1)
Diseases named in the same sentence as LRG1 in open-access papers (continued):
Sharing a sentence is not in itself a finding about the gene and the disease.
tumor (continued). "Several studies showed that LRG1 achieved its part biological function by regulating TGF-β signaling pathway, which plays an important role in the development of tumor." (PMID 26517349, 2015). "In the overall cohort of 777 patients with HCC, LRG1, along with tumor size, tumor multiplicity, serum level of AFP, tumor differentiation, vascular invasion and TNM, were identified as independent prognostic factors." (PMID 26517349, 2015). "LRG1, as well as tumor size, serum AFP level, tumor multiplicity, clinical stage, vascular invasion, and tumor differentiation were shown to be responsible for the outcome of overall survival in both training cohort and validation cohort." (PMID 26517349, 2015). "Although LRG-1 did not correlate with tumor grade or lymph node involvement, our findings on circulating levels of LRG-1 are underpinning its relevance as a marker of poor survival in patients with early BC." (PMID 38413424, 2024). "Reduced tumor cell metastasis, growth, proliferation, and angiogenesis in the absence of LRG1 (in vivo, in vitro)." (PMID 38745756, 2024). "Prokineticin 2(PROK2)is an important contributor to tumor angiogenesis, Ring Finger Protein 213 (RNF213) is essential for normal vascular development, and Leucine Rich Alpha-2-Glycoprotein 1 (LRG1) plays a role in retinal vascularization abnormalities observed in oxygen-induced retinopathy." (PMID 36032067, 2022). "We demonstrate that LRG1 and Magacizumab-LRG1 are predominantly non-internalising, and that a Magacizumab-fluorophore conjugate localises at the tumour site in an in vivo model." (PMID 34458833, 2021). "To evaluate the relevance between LRG1 and clinical outcome, we examined LRG1 expression by immunohistochemistry (IHC) in the tissue microarray (TMA) which consists of tumor specimens of 141 stage I-stage IV CRC patients with up to 5 years of follow-up information." (PMID 34930899, 2021). "Despite the important role of Lrg1 in ocular angiogenesis, no changes were observed in tumour vessel density in xenograft tumours of wild-type and Lrg1-/- mice." (PMID 34208965, 2021). "In clinical CRC tumor samples, LRG1 expression was positively correlated with CAFs-specific marker, α-SMA, and a higher LRG1 expression predicted poor clinical outcomes especially distant metastasis free survival, supporting the role of LRG1 in CRC progression." (PMID 34930899, 2021). "Although it has been clear that LRG1 is involved in a variety of malignant diseases, the molecular mechanism of its regulation of tumor has not been fully clarified." (PMID 32047555, 2020). "In addition, LRG-1 markedly promoted the viability, proliferation, migration and invasion of PDAC cells in vitro and facilitated tumor growth in vivo." (PMID 30760292, 2019). "LRG1 and CD34 were tested in tumor tissues by immunohistochemistry (IHC)." (PMID 29029535, 2017). "Moreover, high expression of leucine-rich α-2-glycoprotein (LRG1) measured by immunohistochemistry in primary tumor, showed a positive correlation rate of 65% with LRG1 presence in urine samples, suggesting that LRG1 in urinary exosomes might be derived from primary tumor tissue." (PMID 26919248, 2016). "Increase of LRG1 expression was significantly correlated with tumor size, tumor differentiation, TNM stage and vascular invasion, suggesting that LRG1 might play a role in HCC progression." (PMID 26517349, 2015). "After validation on tumour and nontumour tissue samples, leucine-rich alpha-2-glycoprotein (LRG1) and inter-alpha-trypsin inhibitor heavy chain H13 (ITIH3) were determined as being overexpressed in tumour tissues; however, their practical use in the clinical environment is questioned." (PMID 24550697, 2014). "Lrg1 is exclusively expressed on tumor ECs rather than normal ECs or pericytes." (PMID 38580870, 2024). "Similarly, studies are lacking using genetically manipulated host- or tumor-derived LRG-1 in BC-bearing animal models." (PMID 38413424, 2024).
tumor (continued). "Cellular distribution and expression level of LRG1 was studied in PCa tissue microarray (TMA) by immunohistochemical staining, which contained paraffin embedded 52 PCa samples with paired adjacent non-tumor samples, 42 unpaired PCa samples and 3 normal prostate samples." (PMID 36681849, 2023). "This may be due to the separation of serum-derived EVs rather than tumor-derived EVs, and the upregulated LRG1 does not necessarily come from the tumor itself." (PMID 34590603, 2021). "In addition, LRG1 promoted VEGF-A expression in CRC cells and contributed to tumor angiogenesis." (PMID 26856989, 2016). "Moreover, we did not observe significant correlations between either A1BG or LRG1 serum expressions and the patient demographics such as subtype, tumor stage or smoking history." (PMID 23284758, 2012). "Thus, coupling the dynamics of circulating LRG1 with components of the immune system throughout the treatment schedule of ADT and RT might provide insights into specific conditions that favor complete tumor regression." (PMID 38386171, 2024). "For instance, data from our recent work on tumour vasculature suggest that LRG1 may also disrupt the normal crosstalk between endothelial cells and pericytes, which is an essential prerequisite of vascular homeostasis, thus making vessels unstable and more prone to sprouting." (PMID 35062948, 2022). "Levels of CEA, CA19.9, PLR, SCF, and LRG1 had non-significant difference in lymph nodes and presence or absence of metastasis in CRC patients and early or late tumor stage (p ≥ 0.05)." (PMID 33492603, 2021). "Additionally, PTC patients with tumor extrathyroidal extension had significantly lower PROS1, CLU, and LRG1 IHC scores compared to patients without extrathyroidal extension (P = .001, P = .001, and P = .001, respectively)." (PMID 40797389, 2025).
infection (17 papers, 2010 to 2026). The state of being infected such as from the introduction of a foreign agent such as serum, vaccine, antigenic substance or organism. "Among the common proteins that were increased in abundance, all (Saa1, Lrg1, Hpx, Hp, Itih4, Serpina3n, Fga/b/g, Cp, and C3) were associated with the acute-phase response to infection." (PMID 32843537, 2020). "Notably, LRG1 emerged as a potential biomarker associated with infection severity, possibly playing a role in suppressing heme toxicity and resisting pathogen infection." (PMID 40447567, 2025). "Leucine-rich alpha-2-glycoprotein 1 and NADH:ubiquinone oxidoreductase subunit B4 are potential biomarkers associated with infection severity." (PMID 40447567, 2025). "Plasma western blot confirmed 44-fold overexpression of LRG1 in the Ad-LRG1-FL group 5 days after infection." (PMID 36346018, 2022). "Most importantly, like other granule proteins, LRG1 can be released into the extracellular space upon neutrophil activation at sites of infection or inflammation." (PMID 35062948, 2022). "Neutrophils act as first responders to infection, which explains the rapid detection of AA by LRG1, as it is secreted by neutrophils." (PMID 34064691, 2021). "Another peculiar facet of LRG1 is the remarkably increased concentration at the local site of inflammation, possibly distinguishing infections based on marked LRG1 deposition." (PMID 34064691, 2021). "Overall, these findings suggest that LRG1 has emerged as a potential biomarker for IE, capable of reflecting infection severity, and might play a role in regulating iron metabolism during IE infection." (PMID 40447567, 2025). "Indeed, several studies have appeared in recent years describing LRG1 as a key player in the organism’s acute response to injury and infections." (PMID 35062948, 2022). "Therefore, the higher level of LRG1 may indicate that the degree of inflammation (and neutrophil activation) during infection is greater in EBOV-infected animals than in Bp-infected animals." (PMID 30774579, 2019). "Of the 9 TN-specific proteins, 6 proteins (CRP, LBP, LRG1, SAA1, TFRC) overlapped with the WT group identifying them as infection-specific and toxin-independent proteins (black text)." (PMID 41326716, 2026). "We also found that the LRG1-mediated restoration of erectile function was slightly attenuated in the presence of a TGF-β1-blocking antibody and was significantly decreased by further infection with shLPHN2 lentivirus." (PMID 35562586, 2022). "Although both LRG1 and G3BP are not filovirus-specific induced proteins, the increased level produced may be useful as blood-based markers to distinguish infection types (bacterial vs. viral) during the acute phase." (PMID 30774579, 2019).
cardiovascular disease (11 papers, 2020 to 2025). "Whilst raised levels of LRG1 have been mostly associated with disease progression, its contribution to cardiovascular disease is less clear with both protective and pathogenic properties being reported." (PMID 35062948, 2022). "LRG1 may serve as a predictive factor for cardiovascular disease in ESRD patients and its pathogenic role warrants further investigation." (PMID 32249825, 2020). "While exerting putative protective functions locally, serum LRG1 has been suggested as a valuable biomarker for the diagnosis and monitoring of various cardiovascular diseases." (PMID 35062948, 2022). "Elevated serum concentrations of leucine-rich α-2-glycoprotein (LRG1) have been reported in patients with inflammatory, autoimmune, and cardiovascular diseases." (PMID 34291056, 2021). "Several bioinformatic analyses have shown that LRG1 may serve as a useful biomarker in cardiovascular diseases." (PMID 38742172, 2024). "Previous studies have shown that an increased concentration of plasma LRG1 was found in inflammatory diseases and cardiovascular diseases, suggesting it may be a potential biomarker." (PMID 37916147, 2023). "Furthermore, elevated serum LRG1 levels were reported in human patients with various inflammatory, autoimmune, and cardiovascular diseases." (PMID 34291056, 2021). "Because transplantation of wild type mouse bone marrow alleviated the change, the authors concluded that LRG1 production from heart-infiltrating myeloid cells improves local angiogenesis, suppresses cardiac remodeling and protects against cardiovascular diseases." (PMID 32249825, 2020). "The involvement of LRG1 in angiogenesis may heighten its importance in cardiovascular disease beyond inflammation." (PMID 32249825, 2020). "Plasma ceramide and LRG1 concentrations were measured with a targeted liquid chromatography-tandem mass spectrometry assay and a Milliplex® MAP human cardiovascular disease magnetic bead kit, respectively." (PMID 35883498, 2022).
kidney disease (8 papers, 2020 to 2025). "Plasma expression levels of LRG1 correlated positively with renal function and renal disease activity, and reflect specific pathologic lesions in the kidneys of patients with LN." (PMID 32252660, 2020). "Notably, elevated levels of circulating CTGF and LRG1 levels are both associated with worse renal outcomes in DKD patients 65, 218, 219, and are causal in kidney disease pathogenesis." (PMID 39990662, 2025). "pLRG1 was elevated in patients with high renal disease activity and LRG1 could be induced by some inflammatory cytokines." (PMID 32252660, 2020). "In plasma, level of LRG1 might be a good indicator of renal function and renal disease activity of LN." (PMID 32252660, 2020). "In addition, higher levels of LRG1 seem to be generally associated with renal function decline in T2DM patients and may serve as a predictor for the risk of kidney disease progression." (PMID 39595649, 2024). "Thus, it remains to be determined whether LRG1 blockade would be of greater utility than pan-TGF-β inhibition, particularly in kidney disease settings." (PMID 39990662, 2025).
retinopathy (6 papers, 2017 to 2025). "Lrg1 gene expression remained low from P5 to P16 compared to expression in oxygen-induced retinopathy where pathogenic vessel growth takes place." (PMID 40277918, 2025). "To examine if the loss of Lrg1 would increase NG2 expression in this setting, we compared hypoxia-induced neovascularization in retinas from P16 wild type (WT) and Lrg1−/− knockout oxygen-induced retinopathy (OIR) littermates." (PMID 40277918, 2025). "For instance, patients with PDR have significantly higher LRG1 levels in the vitreous than non-diabetic controls or diabetic patients without retinopathy." (PMID 35062948, 2022).
bacterial infections (4 papers, 2009 to 2023). "Leucine-Rich Alpha-2-Glycoprotein (LRG1) is a 50 kDa glycoprotein that behaves as an acute phase reactant and has been strongly associated with systemic inflammatory processes, bacterial infections and neoplastic processes." (PMID 37148275, 2023). "Subsequent studies have shown that LRG1 expression increased in hepatocytes in response to mediators of the acute-phase response, and serum LRG1 levels were increased in patients with bacterial infections." (PMID 35329889, 2022). "Subsequent studies have shown that LRG1 expression increases in hepatocytes in response to mediators of the acute-phase response, and serum LRG1 levels are increased in patients with bacterial infections." (PMID 28081565, 2017).
inflammation (4 papers, 2020 to 2025). Aberrant reaction of the microcirculation characterized by movement of fluid and leukocytes from the blood into extravascular tissues. "The current study results also suggested plasma markers and therapeutic targets of prenatal inflammation and related organ responses including renal inflammation, namely, LRG1 and ICA (increased and decreased by IA LPS, respectively)." (PMID 33193334, 2020).
infectious disease (3 papers, 2017 to 2024). A disorder directly resulting from the presence and activity of a microbial, viral, or parasitic agent in humans. "In the basic study of infectious diseases, LRG1 participated in FOS-like 1-regulated gene expression during lipopolysaccharide-induced human lung pulmonary endothelial cell angiogenesis." (PMID 35095520, 2021). "LRG1 provided a novel biomarker for the evolution of cellular microbiology and infectious diseases." (PMID 35095520, 2021). "The glycoprotein leucine-rich alpha-2-glycoprotein 1 (LRG1) mediates protein–protein interaction and contributes to cell adhesion and was observed to be upregulated about 2.5 times in the TBI group compared with the infectious disease group." (PMID 39391051, 2024).
neurological diseases (3 papers, 2022 to 2023). "However, the greater prevalence of neurological disorders in the elderly cohort makes it unclear whether the increase in LRG1 production was caused by age, disease, or both." (PMID 35062948, 2022).
respiratory diseases (2 papers, 2020 to 2021). "Receiver operating characteristics analyses using a 5-protein panel (CFHR5, LRG1, CRP, LBP, and SAA1) exhibited discriminatory power in distinguishing TB from other respiratory diseases (AUC = 0.81)." (PMID 32780727, 2020).
benign tumors (1 paper, 2021). "Our results demonstrated that SCF and LRG1 levels were significantly increased in patients with CRC compared with benign tumors and healthy subjects." (PMID 33492603, 2021). "LRG1 recorded the highest efficiency, specificity, positive prediction, and AUC value (66%, 95% and 96%, 0.84, respectively) as an individual marker for discriminating CRC from benign tumors, while AUC was not improved when LRG1 combined with SCF." (PMID 33492603, 2021).
endocrine diseases (1 paper, 2021). "Furthermore, LRG1 was involved in other endocrine diseases and has key capabilities for the pathological process of diseases." (PMID 35095520, 2021).
immunity diseases (1 paper, 2021). "In basic research related to immunity diseases, interleukin-22 also promoted the expression of ERK1/2 (extracellular signal regulated kinase)-independent genes, such as LRG1, which were involved in inducing cell proliferation in intestinal epithelial cells." (PMID 35095520, 2021).
tumors of the digestive system (1 paper, 2021). "LRG1 was identified as a biomarker for tumors of the digestive system." (PMID 35095520, 2021).
LRG1 also shares sentences with these, for which no sentence is quoted: endometrial carcinoma (5 papers); bladder cancer (3); chronic obstructive pulmonary disease (3); end-stage renal disease (3); hematological malignancies (3); neurodegenerative disease (3); retinoblastoma (3); liver diseases (2); metastatic melanoma (2); multiple sclerosis (2); Myocardial fibrosis (2); oral cancer (2); Parkinson’s (2); acute myocardial infarction (1); acute pancreatitis (1); adenocarcinoma (1); allergic rhinitis (1); autism spectrum disorder (1); babesiosis (1); benign breast tumors (1); bile duct cancer (1); brain glioma (1); brain infarct (1); brain injury (1); choroidal neovascularization (1); chronic periodontitis (1); clear cell renal cell carcinoma (1); cognitive decline (1); coronary artery aneurysms (1); coronary atherosclerosis (1).
A further 52 diseases each share a sentence with LRG1 in 1 paper.